VWA5B2 (von Willebrand factor A domain containing 5B2)
Synonyms: DKFZp761K032; LOC90113
Tractability: No criterion of Open Targets' tractability assessment is met for any kind of drug.
Gene: Protein-coding gene on chromosome 3 (184,228,996 to 184,242,342, forward strand). Ensembl gene ENSG00000145198.
Subcellular location (Human Protein Atlas): Golgi apparatus; Nucleoplasm
Genetic constraint (gnomAD): Loss-of-function variants: 93 observed, 107.61 expected, observed/expected ratio (o/e) 0.86, 90% interval 0.73 to 1.03. The upper end of that interval is the gene's LOEUF score, 1.03, which puts it in group 4 of 6, group 1 being the genes least tolerant of losing a copy. Missense variants: 1,546 observed, 1,575.3 expected, observed/expected ratio (o/e) 0.98, 90% interval 0.94 to 1.02. Synonymous variants: 708 observed, 666.79 expected, observed/expected ratio (o/e) 1.06, 90% interval 1 to 1.13.
Homologues: Orthologues: chimpanzee VWA5B2 (99% identical), macaque VWA5B2 (97% identical), pig VWA5B2 (89% identical), dog VWA5B2 (89% identical), mouse Vwa5b2 (84% identical), rat Vwa5b2 (84% identical), guinea pig VWA5B2 (81% identical), rabbit VWA5B2 (73% identical), tropical clawed frog vwa5b2 (39% identical), zebrafish vwa5b2 (32% identical). Paralogues in human: VWA5B1 (31% identical), VWA5A (16% identical), ITIH6 (10% identical), PARP4 (10% identical), ITIH4 (10% identical), VWA3A (9% identical), VWA3B (9% identical), ITIH3 (9% identical), ITIH5 (9% identical), ITIH1 (9% identical), ITIH2 (9% identical).
Diseases named in the same sentence as VWA5B2 in open-access papers:
VWA5B2 is named in the same sentence as 7 diseases in open-access papers, as found by Europe PMC text mining. Sharing a sentence is not in itself a finding about the gene and the disease. The quoted sentences say what the papers report.
acute liver failure (1 paper, 2022). Rapid deterioration of liver function causing encephalopathy and coagulopathy. "miR-1224, located at chromosome 3q27.1, is a class of mammalian mirtron encompassed in the last intron of the VWA5B2 gene (von Willebrand factor A domain containing 5B2) and is discovered that acts vital roles in some diseases, such as acute liver failure, Parkinson’s disease, and cerebral ischemia." (PMID 35494023, 2022).
prostate carcinoma (1 paper, 2022). A carcinoma that arises from epithelial cells of the prostate gland. "A prognostic model composed of seven protein-coding genes (FOXN4, MGAM, MMP26, ARC, SOX11, PRAME, and VWA5B2) was established, and it was strongly associated with biochemical recurrence following radical prostatectomy in prostate cancer." (PMID 37255653, 2022).
Usher syndrome type 1F (1 paper, 2023). A form of Usher syndrome type IF that can be caused by homozygous or compound heterozygous mutation in the protocadherin-15 gene (PCDH15) on chromosome 10q. "Similarly, VWA5B2 (von Willebrand factor A domain containing 5B2), with unknown biological function, may play a role in Usher Syndrome Type 1f, but its role in pregnancy loss is as yet unknown." (PMID 36800380, 2023).
VWA5B2 also shares sentences with these, for which no sentence is quoted: adenocarcinoma (1 paper); Cerebral ischemia (1); Parkinson disease (1); tumor (1).